TRPM4 (transient receptor potential cation channel subfamily M member 4)
Diseases named in the same sentence as TRPM4 in open-access papers (continued):
Sharing a sentence is not in itself a finding about the gene and the disease.
ischemic stroke (19 papers, 2019 to 2025). A stroke disorder caused by obstruction of blood flow to the brain, due to thrombotic (local blood clot formation) or embolic (due to a blood clot or other material traveling from another site) event. "Dysfunctional TRP channels, particularly TRPM2 and TRPM4, have been implicated in ischemic stroke." (PMID 38300642, 2024). "TRPM4 participates on damage caused by ischemic stroke and spinal cord injury." (PMID 33240883, 2020). "Pharmacological dissociation of the neuronal TRPM4-NMDAR complex or glibenclamide treatment improve the outcome of ischemic stroke-induced brain damage in mice." (PMID 39687019, 2024). "The upregulation of sulfonylurea receptor 1 (SUR1)-TRPM4 channel has been seen in microvascular ECs, astrocytes and pericytes in both humans with stroke and rat models of ischemic stroke." (PMID 38300642, 2024). "The transient receptor potential melastatin 4 (TRPM4) channel has been suggested to play a key role in the treatment of ischemic stroke." (PMID 29569041, 2019). "Evans Blue extravasation and hemoglobin quantification in the ipsilateral hemisphere were greatly reduced, suggesting that TRPM4 inhibition can improve BBB integrity after ischemic stroke reperfusion." (PMID 29569041, 2019). "Genetic ablation or antibody blocking of TRPM4 was shown to be beneficial in mouse models of MS and ischemic stroke without detectable impairments due to loss of TRPM4 function." (PMID 39687019, 2024). "After MCAO, expression of TRPM4 in the endothelial cells was markedly upregulated, and knockdown of TRPM4 protected mice against ischemic brain injury, suggesting TRPM4 activation may promote BBB degradation after ischemic stroke." (PMID 35159300, 2022). "Similarly, the inhibition of TRPM4 expression in a rat ischemic stroke model improved the outcome, although this effect was only transient, in correlation with the ischemia-induced transient increase of TRPM4 expression." (PMID 35056097, 2021). "Importantly, TRPM4 inhibition and silencing improves outcome of both spine cord injury and ischemic stroke." (PMID 33240883, 2020). "Compared to TRPM4, the detrimental effects of TRPM7 in ischemic stroke have been extensively studied since 2003." (PMID 35159300, 2022). "The evaluation of SUR1 ± TRPM4 and pharmacological inhibition of the channel by glibenclamide in primary ICH is less mature than current data in disease subtypes of ischemic stroke and TBI." (PMID 34769328, 2021). "Sur 1 and Trpm4 are both upregulated and co-expressed as the heteromeric Sur1-Trpm4 channel after brain injury, such as ICH, ischemic stroke, and traumatic brain injury." (PMID 31042750, 2019). "In addition to TRPM2, TRPM4 and TRPM7 are also highly expressed in the brain, and were found to aggravate the brain injury following ischemic stroke." (PMID 35159300, 2022).
cardiac hypertrophy (16 papers, 2014 to 2025). "Although the causative link between TRPM4 mutations and conduction problems is clearly established, TRPM4 can also be involved in other cardiac problems such as cardiac hypertrophy." (PMID 35056097, 2021). "Cardiovascular risks have a detrimental impact on human health, and some research has implicated TRPM4 in cardiac hypertrophy, myocardial ischemia-reperfusion injury (IRI), and hereditary arrhythmia." (PMID 29914130, 2018). "At 32 weeks old, cardiac hypertrophy persisted in Trpm4-/- mice and was associated with diastolic dilation." (PMID 25531103, 2014). "Furthermore, global deletion of Trpm4 causes eccentric cardiac hypertrophy with aging which is caused by neonatal cardiomyocyte hyperplasia." (PMID 33013458, 2020). "Thus, TRPM4 is an essential regulator of the hypertrophic alteration and is likely to supply a novel direction for the treatment of cardiovascular diseases caused by cardiac hypertrophy." (PMID 29914130, 2018). "Piezo1 is known to act together with other TRP channels: in response to pressure overload, Piezo1 transduces mechanical signals to TRPM4 channels in cardiac hypertrophy, and Piezo1 cooperates with TRPV4 channels in pressure-induced pancreatitis." (PMID 40019468, 2025). "Trpm4 knock-out C57Bl/6 mice are known to develop cardiac hypertrophy with perturbation of electrical activity." (PMID 36982932, 2023). "In the present study, we employed mice subjected to TAC as an in vivo cardiac hypertrophy model to investigate the role of the TRPM4 ion channels in pressure overload-induced pathological LVH." (PMID 34190686, 2021). "Other studies indicate that TRPM4 contributes to both cardiac function and disease development, including cardiac hypertrophy and heart failure." (PMID 34190686, 2021). "In a cardiomyocyte-specific Trpm4 knockout mouse (Trpmcko), induction of cardiac hypertrophy with ANG-II resulted in increased hypertrophy in Trpm4cko mice when compared to controls." (PMID 33013458, 2020). "The role of TRPM4 in cardiac hypertrophy has also been reported by Guinamard and collaborators, who observed an increase in TRPM4 expression in spontaneously hypertensive rats, while no expression was detected in control rats." (PMID 33291725, 2020). "Recently, a study confirmed the beneficial role of TRPM4 in hard training-induced physiological hypertrophy because TRPM4 knockout mice developed a pathological cardiac hypertrophy when they were subjected to endurance training." (PMID 30881310, 2019). "Increased mRNA expression of TRPM4 was detected in spontaneously hypertensive rats, a model of cardiac hypertrophy." (PMID 31315301, 2019). "TRPM4 is important for the beneficial cardiac remodeling induced by endurance training, and the role of TRPM4 in physiological and pathological cardiac hypertrophy has also been studied." (PMID 29914130, 2018). "To evaluate the effect of TRPM4 on the development of cardiac hypertrophy, we performed chronic angiotensin II (AngII) infusion in WT and Trpm4cKO mice." (PMID 26043922, 2015). "Taken together, our data describe the role of TRPM4 in the development of AngII-induced pathological cardiac hypertrophy." (PMID 26043922, 2015). "Trpm4-/- mice exhibited cardiac hypertrophy, higher cellular density and smaller LV cardiomyocytes size at the age of 12 weeks." (PMID 25531103, 2014). "Trpm4-/- mice exhibited moderate cardiac hypertrophy at 6 months of age, as well as ventricular dilation." (PMID 25531103, 2014). "We observed that increased hyperplasia in Trpm4-/- mice during the neonatal stage influences the adult left ventricular mass resulting in eccentric cardiac hypertrophy." (PMID 25531103, 2014). "Intriguingly, using the same cardiomyocyte-specific Trpm4 KO mice, TRPM4 channels were shown to act differently as either negative or positive regulators for angiotensin II-induced cardiac hypertrophy and pressure overload-induced cardiac hypertrophy." (PMID 37511555, 2023).
cardiac hypertrophy (continued). "Indeed, TRPM4 was shown to be indirectly involved in the regulation of the calcineurin–NFAT pathway in a model of pressure-overload-induced cardiac hypertrophy in mice." (PMID 36139640, 2022). "Moreover, further highlighting the importance of TRPM4 in the ventricle, it was shown that the presence of TRPM4 reduces the angiotensin-II-induced cardiac hypertrophy." (PMID 34502410, 2021). "TRPM4 channel is Ca2+-activated, Na+- and K+-permeable and its increased expression can probably participate in development of delayed after-depolarizations (DADs) during cardiac hypertrophy." (PMID 31315301, 2019). "Indeed, TRPM4 has been shown to play a role in cardiac hypertrophy by the construction of a typical model that mimics the ventricular hypertrophic alteration in spontaneously hypertensive rats (SHRs)." (PMID 29914130, 2018). "TRPM4 is a negative regulator of cardiac hypertrophy induced by angiotensin II (AII) stimulation." (PMID 29914130, 2018). "However, the heart weight to BW ratio was higher in Trpm4-/-animals (9.29±0.44 vs. 6.5±0.28 a.u. in Trpm4+/+ mice, n = 6 and 5 respectively) indicating cardiac hypertrophy." (PMID 25531103, 2014). "Thus, the finding of a similar interaction between Piezo1 and TRPM4 opens an attractive possibility of developing novel compounds targeting specifically the Piezo1/TRPM4 interface for treatment of cardiac hypertrophy and possibly other cardiac mechanochannelopathies." (PMID 40869375, 2025). "Indeed, TRPM4 was shown to participate in pressure overload-induced cardiac hypertrophy in mice." (PMID 36982932, 2023). "Special attention has been given to TRPC’s role in cardiac hypertrophy, but the implication of TRPV1, TRPV2, and TRPM4 has been also demonstrated." (PMID 30881310, 2019). "Echocardiography confirmed cardiac hypertrophy as Trpm4-/- mice exhibited an increase in left ventricular mass (LVM corrected and normalized to BW was 4.10±0.63mg/g, n = 6 vs.3.06±0.1, n = 7 in Trpm4+/+ mice, P<0.01)." (PMID 25531103, 2014). "Unlike with cardiac hypertrophy induced by hypertension, TRPM4 mRNA remained unchanged during both 25 min of ischemia and the following 40-min-long reperfusion in rats." (PMID 35056097, 2021). "The role of TRPM4 in cardiac hypertrophy is controversial and it seems to work as a negative regulator of cardiac hypertrophy development after angiotensin II infusion." (PMID 31315301, 2019). "In this study, we demonstrated the effect of the calcium-activated non-selective cation channel TRPM4 on the development of cardiac hypertrophy upon chronic AngII infusion." (PMID 26043922, 2015). "Our functional recordings using cardiac magnetic resonance imaging revealed a ventricular hypertrophy without modification of the ejection fraction in Trpm4−/− animals compared to Trpm4+/+ mice, in accordance with previous observations made using echography measurements in this mouse strain." (PMID 36139640, 2022).
Brugada syndrome (15 papers, 2014 to 2025). "To date, more than 25 variants of TRPM4 are associated with conduction disorders and Brugada syndrome." (PMID 33810249, 2021). "TRPM4 mutations are linked to cardiac conduction problems such as atrioventricular conduction block, Brugada syndrome, right bundle branch block, and congenital long QT syndrome." (PMID 35056097, 2021). "Any change in the resting membrane potential induced by TRPM4 mutations can reduce sodium-channel availability and contribute to Brugada syndrome." (PMID 35056097, 2021). "Pathogenic mutants in TRPM4 have been reported in patients with inherited cardiac diseases, including conduction blockage and Brugada syndrome." (PMID 33810249, 2021). "Several TRPM4 polymorphisms, most of them in Brugada syndrome patients, were identified and based on the variable clinical phenotypes of both point mutations and polymorphisms." (PMID 35056097, 2021). "Many pathogenic variants of the TRPM4 gene have been identified in patients with different forms of cardiac disorders such as conduction defects, Brugada syndrome, and congenital long QT syndrome." (PMID 33381229, 2020). "4- TRPM4 mutations were reported in patients with other cardiac electrical disturbances such as, cardiac conduction block and Brugada syndrome." (PMID 28315637, 2017). "Recent literature has reported that human Trpm4 gene mutations generate conductions disorders such as right bundle branch blocks or Brugada syndrome." (PMID 25531103, 2014). "Mutations in the Trpm4 gene were recently associated with several human conduction disorders such as Brugada syndrome." (PMID 25531103, 2014). "Moreover, mutations in TRPM4 have been found in cardiovascular diseases, including bundle-branch block and Brugada syndrome." (PMID 34771564, 2021). "Very recently, TRPM4 mutations were among the multiple genes associated with Brugada syndrome." (PMID 35056097, 2021). "Indeed, mutations in human TRPM4 are linked to conduction disorders, such as right bundle branch blockage, Brugada syndrome, and atrioventricular blockage." (PMID 33810249, 2021). "TRPM4 mutations were reported in 6% of Brugada syndrome patients." (PMID 35056097, 2021). "Moreover, in the Brugada syndrome, both gain of function as well as loss of function of TRPM4 channel has been described." (PMID 25531103, 2014). "Pathological variants in TRPM4 gene have been linked to several cardiac phenotypes such as complete heart block (CHB), ventricular tachycardia, and Brugada syndrome (BrS)." (PMID 29568272, 2018). "The involvement of TRPM4 in several pathologies is reminiscent to the voltage-gated Na+ channel encoded by SCN5A, which was associated with LQTS, Brugada syndrome, and conduction blocks." (PMID 28315637, 2017). "Moreover, a study identified the TRPM4 mutation G844D which, upon digenic inheritance with a mutation in SCN5A, was responsible for Brugada syndrome." (PMID 35056097, 2021). "Recent studies have linked genetic variants of TRPM4 gene to progressive familial heart block type 1 (PFHB1), isolated cardiac conduction disease (ICCD), atrio-ventricular block (AVB), right bundle branch block (RBBB) and Brugada syndrome (BrS)." (PMID 29568272, 2018). "Variants in the TRPM4 gene have been associated with ICCD, Brugada syndrome, and heart block." (PMID 26636822, 2015). "Variants in these genes are related to Brugada syndrome, long QT syndrome 15, progressive familial heart block type IB and long QT syndrome 1.26–28 Moreover, five are variants of unknown significance (VUS) and were assessed in KCN5A, TRPM4 and SCNA5 genes." (PMID 39347728, 2024).
cardiac conduction disorders (13 papers, 2013 to 2025). "During the past 15 years, TRPM4 dysfunction has been linked to several cardiac conduction disorders." (PMID 41195386, 2025). "Rare genetic alterations in the TRPM4 gene can cause familial cases of progressive cardiac conduction defects (PCCDs)." (PMID 41195386, 2025). "Clinical studies have reported a strong link between TRPM4 genetic variants and cardiac conduction disorders." (PMID 37604672, 2023). "Variants in TRPM4 have been linked to cardiac conduction diseases, primarily right bundle branch block and atrioventricular block." (PMID 33797204, 2021). "As previously reported, several studies have linked many genetic variants of the TRPM4 gene to different forms of cardiac conduction diseases." (PMID 33381229, 2020). "Within these genes, a growing number of TRPM4 variants have been associated with different forms of cardiac conduction disease." (PMID 33381229, 2020). "Mutations in the TRPM4 gene (including mutations in the C-terminal part of TRPM4) have been reported to cause familial cases of progressive cardiac conduction disease and heart block." (PMID 32560560, 2020). "Recently, other studies have also illustrated that TRPM4 mutations are associated with isolated cardiac conduction disease, right bundle-branch block, tachycardia, and Brugada syndrome." (PMID 29914130, 2018). "This calcium-activated, monovalent, selective cation channel also plays a key role in cardiovascular pathophysiology; for example, a mutation in the TRPM4 channel leads to cardiac conduction disease." (PMID 29914130, 2018). "In conclusion, decreased or increased protein expression of several TRPM4 variants linked to cardiac conduction disorders or ventricular arrhythmias were found to be caused by altered TRPM4 half-life compared to the WT form." (PMID 29568272, 2018). "These include amongst others sensor activity for a wide range of hypertrophic stimuli and mutations in TRPM4 are now recognized as causes of human cardiac conduction disorders." (PMID 23690787, 2013). "TRPM4 dysfunction has been linked to several cardiac conduction disorders." (PMID 37604672, 2023). "Although the first mutation reported in TRPM4 was a gain-of-function mutation linked to progressive heart blockage, several later studies reported both gain- and loss-of-function mutations in TRPM4 related to different cardiac conduction disorders." (PMID 33810249, 2021). "The importance of TRPM4 in disease has been underlined by the observation that many pathogenic genetic variants have been found in patients with cardiac conduction disorders, and that TRPM4 knock-out mice develop less neurological alterations in a mouse model of multiple sclerosis." (PMID 24605085, 2014). "Our results revealed an altered protein turnover in loss- and gain-of-expression mutant compared to the WT form of TRPM4, showing that altered half-life of TRPM4 is one of the mechanisms leading to several cardiac conduction disorders." (PMID 29568272, 2018). "Based on these contrasting results, the involvement of SUMOylation and/or ubiquitination leading to increased TRPM4 expression in patients with cardiac conduction disorders still remains to be elucidated." (PMID 29568272, 2018). "In the present study, we performed genetic analysis of the TRPM4 gene in patients to elucidate its role in various types of cardiac conduction disorders or ventricular arrhythmias." (PMID 29568272, 2018). "The pathophysiological role of TRPM4 in cardiac conduction disease and BrS remains unclear." (PMID 33381229, 2020). "Thus, it’s tempting to speculate that additional factors then gain-of-function of TRPM4 channel activity per se lead to cardiac conduction disorders." (PMID 31316392, 2019).
ischemia (13 papers, 2015 to 2024). A hypoperfusion of the BLOOD through an organ or tissue caused by a PATHOLOGIC CONSTRICTION or obstruction of its BLOOD VESSELS, or an absence of BLOOD CIRCULATION. "Following ischemia, the TRPM4 channel colocalized and associated with Sur1 within ischemic endothelial cells and neurons." (PMID 36527242, 2023). "A pilot porcine study after malignant MCA infarction also demonstrated elevated SUR1 and TRPM4 expression in the core (highest levels) and penumbra, as well as in contralateral neurons and microvessels 5 h after ischemia." (PMID 34769328, 2021). "In conclusion, our data have uncovered a previously unknown function of TRPM4 on cell swelling during acute ischemia/hypoxia." (PMID 33195194, 2020). "We first examined the effect of TRPM4 blockade on endothelial cells following ischemia reperfusion." (PMID 29569041, 2019). "It is tempting to speculate that the inhibition of TRPM4 activity may prevent calcium overload during ischemia-reperfusion injury." (PMID 25836769, 2015). "Suppression of the Na(+)-K(+)-2Cl(-) cotransporter, NKCC1, and the trauma-/ischemia-induced SUR1-regulated NC(Ca-ATP) (SUR1/TRPM4) channel by bumetanide and glibenclamide, respectively, show reduction of capillary failure in rats following TBI and ischemia." (PMID 32397302, 2020). "These in vivo data collectively demonstrate that TRPM4 inhibition could protect BBB integrity and reduce tissue damage following ischemia reperfusion." (PMID 29569041, 2019).